PCDH19 (protocadherin 19)
Diseases named in the same sentence as PCDH19 in open-access papers (continued):
Sharing a sentence is not in itself a finding about the gene and the disease.
epilepsy (continued). "Other genetic epilepsies that can benefit from precision therapy include KCNQ2 (carbamazepine, phenytoin), GLUT1 deficiency, SLC2A1 or CDKL5 (ketogenic diet), PCDH19 (clobazam), mutations in KCNQ2, SCN2A, and SCN8A (ion sodium channel blockers), and mTORopathies (mTOR inhibitors)." (PMID 36980114, 2023). "Interestingly, SMC1A-DEE and PCDH19 clustering epilepsy share some epilepsy-related features, e.g., drug resistance and seizure clustering." (PMID 37107610, 2023). "PCDH19 epilepsy among men due to mosaicism is rare but probably underdiagnosed." (PMID 35860011, 2022). "AKR1C1-3 seems to be key in the pathophysiology of PCDH19-related epilepsy." (PMID 35822151, 2022). "A ketogenic diet has been studied to treat several refractory epilepsies, including PCDH19; it has promising results as effective adjuvant therapy in the resolution of status epilepticus, suggesting it could be used as part of the treatment in early childhood." (PMID 36004035, 2022). "Clinical features of 11 mosaic male patients with PCDH19-related epilepsy in our cohort." (PMID 36408521, 2022). "Till now, the pathophysiology of the disease is mainly unknown, so we conducted a literature review to elucidate the pathophysiology of PCDH19-related epilepsy." (PMID 35822151, 2022). "Patients with PCDH19-CE suffer from epilepsy already early after birth." (PMID 36389226, 2022). "Clinical, EEG and MRI characteristics and treatment efficacy in PCDH19-related epilepsy." (PMID 35111125, 2021). "The clinical presentation of PCDH19-related epilepsy often overlaps with that of GEFS+." (PMID 35111125, 2021). "The terms “PCDH19” and “PCDH19” epilepsy were used in this systematic search." (PMID 35111125, 2021). "Future research in mouse models of PCDH19 epilepsy should elucidate whether BBB disruptions are a feature of the syndrome and what molecular pathways are involved in this pathogenesis." (PMID 34209535, 2021). "Genetic epilepsies caused by deletions, such as in NRXN1 and selected cases of PCDH19, could be potentially treated using these approaches." (PMID 34235638, 2021). "Indeed, the BBB disruption, as we have already seen in previous paragraphs, appears to be common in neural pathologies that show co-morbidity with epilepsy, such as PCDH19 epilepsy, glioblastoma and multiple sclerosis." (PMID 34209535, 2021). "Among these genes, PCDH19 has been reported to be closely related to epilepsy." (PMID 34261484, 2021). "Pathogenic PCDH19 variants and CNV changes affect this gene in epilepsy." (PMID 33557955, 2021). "Next, we assessed nine seizure-related features, including “febrile”, “tonic–clonic”, “myoclonic”, “complex partial seizure/absence”, and “status”, as well as behavioral features, including autistic and behavioral disturbances, in patients with PCDH19-related epilepsy." (PMID 33262389, 2021). "Protocadherin 19 (PCDH19)-related epilepsy is an epileptic syndrome with various characteristics." (PMID 33262389, 2021). "A possible involvement of neuroinflammation has been proposed for PCDH19 epilepsy." (PMID 34209535, 2021). "The disorder, which was first reported fifty years ago by Juberg and Hellman, represents one of the most diffuse monogenetic epileptic forms in the pediatric population, and recent molecular epidemiologic studies indicate PCDH19 as the second most clinically relevant gene in epilepsy after SCN1A." (PMID 34201522, 2021). "Therefore, special attention should be paid to the detection of PCDH19 in female with early onset epilepsy." (PMID 33287870, 2020).
epilepsy (continued). "For some genes, such as GRIN2A, which codes for severe forms of idiopathic focal epilepsy, and PCDH19, which has similarities to Dravet syndrome, the therapeutic concepts of these forms of epilepsy may also apply to these genes." (PMID 33519703, 2020). "Even though spontaneous epilepsy has not been reported, increased seizure susceptibility has been observed both in rats, in which PCDH19 had been downregulated in a subset of hippocampal neurons, and in PCDH19 KO mice." (PMID 33352832, 2020). "The characteristic phenotype for PCDH19 heterozygous females and mosaic males is epilepsy." (PMID 32366910, 2020). "PCDH19-related epilepsy is characterised by fever sensitivity." (PMID 31784560, 2019). "In this study, we disclose a previously unknown role of PCDH19 in regulating GABAergic transmission in an attempt to provide insights into the phenotype of PCDH19-FE, characterized by epilepsy and intellectual disability." (PMID 29360992, 2018). "Important non-classic cadherin implicated in genetic cases of epilepsy is protocadherin-19 (PCDH19)." (PMID 30298130, 2018). "Up to now, the molecular genetic study for PCDH19-related epilepsy has been focused on females." (PMID 29866057, 2018). "Individuals with epilepsy associated with mutations in the PCDH19 gene display generalized or focal seizures with or without fever sensitivity." (PMID 29866057, 2018). "The last mutation, D417H, is not involved in any known interface, but this epilepsy patient has a pair of mutations in PCDH19 (D417H and D596Y)." (PMID 27787195, 2016). "In the present study, we have screened 150 unrelated probands with diverse epilepsy subtypes with or without cognitive impairment or mental retardation in order to define the mutational and clinical spectra associated with PCDH19 mutations." (PMID 21053371, 2011). "Five males (families 2, 6 and 8) were asymptomatic carriers of PCDH19 mutations, they were healthy, had no cognitive impairment or epilepsy, and none had histories of febrile seizures." (PMID 19214208, 2009). "PCDH19 was therefore an attractive candidate gene for epilepsies and mental retardation." (PMID 19214208, 2009). "In conclusion, genetic testing of PCDH19 as the second most important gene in patients with fever-provoked, intractable, infantile epileptic encephalopathy could play a crucial role in the therapy and prognosis of epilepsy." (PMID 38891919, 2024). "Protocadherin 19 (PCDH19) pathogenic variants cause the infantile encephalopathy Clustering Epilepsy (CE, previously known as Girls Clustering Epilepsy; GCE, Female-Limited Epilepsy; FE and Epilepsy and Mental Retardation Limited to Females; EFMR: OMIM #300088)." (PMID 38280856, 2024). "Differential SMC1A insufficiency in SMC1A-DEE individuals with random XCI could further lead to cellular interference (i.e., interference between cells with differential levels of SMC1A) at tissue levels, similar to the proposed for the etiology of PCDH19 clustering epilepsy." (PMID 37107610, 2023). "Here we report hemizygous PCDH19 mutations in two males with autism without epilepsy." (PMID 36980870, 2023). "Monogenic epilepsies can be characterized according to the gene function affected: Impaired function of ion channels (e.g., CACNA1A), receptors (e.g., GABRB3), transporters (e.g., SLC2A1), synapse-related (e.g., PRRT2), and other pathways (e.g., CDKL5, PCDH19) are associated with epilepsy." (PMID 38125836, 2023). "While epilepsy in EFMR patients has been shown to follow this peculiar genotype-phenotype expression pattern, it remains unclear whether it applies to other symptoms of PCDH19 mutation." (PMID 36980870, 2023). "To date, three cases of mosaic PCDH19 variants in males without epilepsy have been reported." (PMID 36408521, 2022). "However, epilepsy caused by mutations in protocadherin 19 (PCDH19) causes epilepsy in females that are heterozygous but not in males that are hemizygous." (PMID 33923061, 2021).
epilepsy (continued). "Besides SCN1A, PCDH19 is among the most relevant genes in epilepsy." (PMID 35111125, 2021). "Indeed, such a mechanism of action could explain why PCDH19 epilepsy patients respond so rapidly to corticosteroid treatment." (PMID 34209535, 2021). "Protocadherin 19 (PCDH19), a human epilepsy driver gene, is expressed primarily in the human brain, as its mutations have been found in early-onset female-restricted seizures and cognitive disabilities." (PMID 37047373, 2023). "In order to investigate whether variants located in the cytoplasmic domain region were lethal or noncausal variants of PCDH19-related epilepsy, we compared the CDFs of missense variants with those of variants from healthy individuals in gnomAD database, including various ethnic backgrounds." (PMID 33262389, 2021). "Moreover, the most supported pathogenic mechanism of PCDH19-related epilepsy is mosaicism of two cell populations, expressing either normal or mutant PCDH19 protein, which is expected to prevent the normal homophilic adhesive function of PCDH19 proteins." (PMID 33262389, 2021). "Mosaicism in the proband has been reported in other genes such as PCDH19 (8.3%, 6/73), SCN1A (1.3%, 4/320), SCN2A (6.4%, 7/110), and CDKL5 (8.8%, 8/91), according to a recent large‐scale study of epilepsy‐related neurodevelopmental disorders." (PMID 30891744, 2019). "Here, we present evidence of three mutations of the PCDH19 gene in a mosaic male and two unrelated females in Chinese individuals with epilepsy, further contributing to the clinical understanding of EFMR in relation to the PCDH19 gene." (PMID 29866057, 2018). "We find current evidence for this preferential enrichment among six epilepsy genes: CDKL5 (P = 1.1 × 10−12), KCNQ2 (P = 1.1 × 10−23), PCDH19 (P = 0.003), SCN1A (P = 9.7 × 10−9), SCN2A (P = 1.9 × 10−4), and SCN8A (P = 3.5 × 10−4)." (PMID 28864458, 2017). "Although fever is reported as a trigger for seizures in girls with PCDH19-related epilepsy, initial presentation of abdominal pain in children has not been previously reported in the context of PCDH19-related epilepsy." (PMID 39792735, 2025). "A distinguishing aspect of PCDH19 epilepsy is that it presents in heterozygous females but not in hemizygous males, with males instead generally showing normal neurologic functioning." (PMID 38424476, 2024). "These two cases present with a CDKL5 and PCDH19 phenotype, respectively, rather than the common features of KS in terms of onset age, epilepsy type, and hypogonadism." (PMID 37479950, 2023). "The clinical characteristics of PCDH19-related epilepsy are epileptic and non-epileptic symptoms with highly variable severity among patients." (PMID 35978409, 2022). "Treatment of PCDH19-related epilepsy is limited by drug resistance and by the absence of specific treatment indications." (PMID 35111125, 2021). "CSNK2B-related epilepsy had some seizures occurred during febrile disease, but, unlike PCDH19-related epilepsy, the seizures does not have significant fever sensitivity." (PMID 31784560, 2019). "Overall our initial characterization of Pcdh19(+/β-Geo), Pcdh19(β-Geo/β-Geo) and Pcdh19(Y/β-Geo)mice reveals that despite widespread expression of Pcdh19 in the CNS, and its role in human epilepsy, its function in mice is not essential for brain development." (PMID 27240640, 2016). "Last but not least, while epilepsy in EFMR patients has been shown to follow a peculiar genotype-phenotype expression pattern, it remains unclear whether it also applies to PCDH19-linked autism." (PMID 36980870, 2023). "Cellular interference is not unique to PCDH19-related epilepsy." (PMID 35822151, 2022).
epilepsy (continued). "More recently, SMC1A truncating variants have been described as the cause of a neurodevelopmental disorder with early-childhood onset drug-resistant epilepsy with seizures that occur in clusters, similar to that seen in PCDH19-related epilepsy, but without the classical features of CdLS." (PMID 35712061, 2022). "Furthermore, the higher levels of Bmal1 and PCDH19 were detected in patients with no hippocampal sclerosis (no HS) than in patients with HS International League Against Epilepsy (ILAE) type I and III." (PMID 34261484, 2021). "In fact, it is important to note that Patient 2, with a similar duplication of the PCDH19 gene and neighboring genes in hemizygous state, showed a very different phenotype, with a growth deficit, developmental delay, and ASD but not epilepsy." (PMID 39457436, 2024).
Intellectual disability (28 papers, 2014 to 2025). "Two female patients carried the same PCDH19 frameshift variant (c.1091dup, p.Y366Lfs*10), presenting with intellectual disability, scoliosis, dermatological symptoms, and, in one, menstrual irregularity." (PMID 41153369, 2025). "Protocadherin-19 (PCDH19) gene mutations cause an infantile-onset epilepsy syndrome with limbic seizures, typically occurring in clusters and variably associated with intellectual disability and a range of psychiatric disorders including autistic features." (PMID 38238304, 2024). "PCDH19 female limited epilepsy (PCDH19-FE) was an infantile-onset epilepsy syndrome with strong phenotype heterogeneity, and hallmark features of PCDH19-FE included focal seizure, intellectual disability, anti-seizure therapy resistance, etc.." (PMID 36970538, 2023). "Human mutations in the protocadherin-19 (PCDH19) gene, which encodes for the PCDH19 protein, also cause early infantile epileptic encephalopathy, associated with intellectual disability and autistic features, similar to Dravet syndrome." (PMID 30899215, 2019). "Mutations in protocadherin 19 (PCDH19), which is on the X-chromosome, cause the brain disease Epilepsy in Females with Mental Retardation (EFMR)." (PMID 31747920, 2019). "The PCDH19 mutations are responsible for female-restricted epilepsy with mental retardation (EFMR) that has been classified as infantile familial or sporadic epilepsy in female patients with or without intellectual disability." (PMID 30298130, 2018). "Disruptions of SWA in PCDH19 patients would therefore likely affect their cognitive performance and might partly underlie the intellectual disability frequently associated with the disease." (PMID 35741068, 2022). "Pathogenic variants in PCDH19 are associated with early onset, clustered epileptic seizures often provoked by fever, intellectual disability (ID) that can be present in variable degrees and behavioural disturbances such as autistic features, attention deficit, hyperactivity and aggression." (PMID 28669061, 2017). "Mutations in the PCDH19 gene on chromosome X (Xp22.1) cause a female-limited epilepsy (PCDH19 Female Epilepsy, PCDH19-FE; OMIM # 300088) that is frequently associated with intellectual disability and autistic features." (PMID 29360992, 2018). "Mutations in PCDH19 cause an X-linked, female-limited form of infant-onset epilepsy (PCDH19 female epilepsy, PCDH19-FE; OMIM 300088) that is associated with intellectual disability, as well as compulsive or aggressive behavior and autistic features." (PMID 27787195, 2016). "The clinical features of the PCDH19 gene mutation include febrile epilepsy ranging from mild to severe, with or without intellectual disability, cognitive impairment, and psych-behavioral disorders, but there has been little research on males with the mosaic mutation of PCDH19." (PMID 36247776, 2022). "We conclude that the age of seizure onset and the presence of intellectual disability may depend not on the type and localization of PCDH19 mutations, but on the X-inactivation status." (PMID 33087045, 2020). "PCDH19-related epilepsy manifested various clinical features, including febrile epilepsy, with or without intellectual disability, and psych-behavioral disorders." (PMID 39792735, 2025).